CBX7 (chromobox 7)
Diseases named in the same sentence as CBX7 in open-access papers (continued):
Sharing a sentence is not in itself a finding about the gene and the disease.
gastric cancer (continued). "Taken together, these results conceivably implicate that CBX7 facilitates cancer stem cell characteristics of gastric cancer cells via the downregulation of p16." (PMID 29422082, 2018). "In the current study, we revealed that high expression of CBX7 in gastric carcinoma was positively correlated with lymph node metastasis and clinical stage." (PMID 29422082, 2018). "Overexpression of CBX7 in gastric cancer tissues correlated with patients' age, clinical stage and lymph node metastasis." (PMID 20723236, 2010). "In the present study we provide in vitro and in vivo evidences to support the oncogenic role of CBX7 in gastric cancer development." (PMID 20723236, 2010). "Here, we show that CBX7 is overexpressed in gastric cancer cell lines and gastric cancer tissues, and its expression correlates with patients' age, clinical stage, lymph node metastasis, and poor prognosis." (PMID 20723236, 2010). "We also report that knockdown of CBX7 expression in gastric cancer cell lines results in induction of a senescence-like phenotype and reduction of transformed properties, which is accompanied by upregulation of p16(INK4a)." (PMID 20723236, 2010). "Cellular senescence, anchorage independent growth, and cell migration assays were performed to determine the functional role of CBX7 in gastric cancer cells." (PMID 20723236, 2010). "The expression level of CBX7 was lower in patients with older age, and higher in patients with late clinical stage, or positive lymph node metastasis, which suggested that overexpression of CBX7 correlated with a more aggressive phenotype in gastric cancer." (PMID 20723236, 2010). "The results suggest that overexpression of CBX7 correlates with poor prognosis in patients with gastric cancer." (PMID 20723236, 2010). "Our results showed that compared to GES-1, a normal immortal human gastric mucosal epithelial cell line, 3 out of 8 gastric cancer cell lines expressed obviously high CBX7 at protein level." (PMID 20723236, 2010). "In the present study, we found that upregulating the expression of PRC1 component Cbx7 in gastric cancer cell lines MGC803 and BGC823 led to significantly suppress the expression of genes within the p16-Arf-p15 locus." (PMID 21060834, 2010). "Does CBX7 also play a role in the carcinogenesis and progression of gastric cancer needs to be studied." (PMID 20723236, 2010). "The expression of CBX7 and its potential target protein p16(INK4a) in gastric cancer cell lines and gastric tumors was assayed by Western blot analysis and immunohistochemistry(IHC)." (PMID 20723236, 2010). "Knockdown of CBX7 expression in gastric cancer cells led to increased cellular senescence, decreased cellular proliferation and migration ability, accompanied by upregulation of p16(INK4a)." (PMID 20723236, 2010). "Our in vitro study also showed that knockdown of CBX7 expression inhibited the ability of migration in gastric cancer cells." (PMID 20723236, 2010). "Then, we examined the expression of p16(INK4a) in control and CBX7 knockdown SGC-7901 cells to determine the possible mechanism of decreased transformed phenotype in gastric cancer cell lines by knockdown of CBX7 expression." (PMID 20723236, 2010). "On the other hand, Cbx7 positively regulates the stem cell-like properties of gastric cancer cells." (PMID 36361869, 2022). "Notably, CBX7 positively regulates stem cell-like characteristics through activation of the Akt-NF-κB pathway and inhibition of p16 in gastric cancer." (PMID 31709304, 2019). "Therefore, it is possible that CBX7 also regulates stem cell-like characteristics of gastric cancer via the repression of p16." (PMID 29422082, 2018). "These experimental results validated the hypothesis that CBX7 could regulate proliferation and stem cell-like properties of gastric cancer cells through the activation of Akt pathway." (PMID 29422082, 2018). "Our previous study found that CBX7 is overexpressed and plays an oncogenic role in gastric cancer." (PMID 29422082, 2018).
gastric cancer (continued). "Because PcG protein BMI1 may regulate AKT and ERK pathways, we analyzed the expression of total AKT, phospho-AKT(p-AKT), total ERK and phospho-ERK (p-ERK) in control, CBX7-overexpressing (CBX7-oe), and CBX7-shRNA (CBX7i) gastric cancer cell lines." (PMID 29422082, 2018). "In summary, our experimental results showed that CBX7 could regulate gastric cancer stem cell phenotype by inhibiting p16INK4a." (PMID 29422082, 2018). "Next, we determined whether constitutive activation of AKT in gastric cancer cells can overcome the GCSC phenotype inhibiting effect of CBX7 shRNA." (PMID 29422082, 2018). "In summary, these results strongly support the hypothesis that CBX7 regulates the transcriptional activity of NF-κB in gastric cancer cells by modulating AKT activation." (PMID 29422082, 2018). "Indeed, our studies strongly suggest that CBX7 regulates expression of p16 in p16-expressing gastric cancer cell lines SGC-7901 and AGS." (PMID 29422082, 2018). "Thus, our data strongly suggest that CBX7 regulates stem cell-like properties of gastric cancer cells through AKT pathway." (PMID 29422082, 2018). "Functional studies showed that CBX7 could promote the growth of gastric cancer cells and colony formation, suggesting an oncogenic role in gastric carcinoma." (PMID 29422082, 2018). "Finally, the pathways by which CBX7 regulates stem cell-like properties of gastric cancer were explored." (PMID 29422082, 2018). "In this study, we found that overexpression of CBX7 in gastric carcinoma cells led to increased expression of phosphorylated AKT (pAKT) and phosphorylated EKR (pERK), while knockdown of CBX7 decreased the levels of pERK and pAKT, suggesting that CBX7 can regulate AKT and EKR pathways." (PMID 29422082, 2018). "What's more, CBX7 in gastric cancer and ovarian cancer were reported as an oncogene, too." (PMID 28388562, 2017). "We have found that Bmi-1 and CBX7 were overexpressed in gastric cancer tissues and correlated with cancer progress and prognosis, while Mel-18 expression inversely correlated with Bmi-1 expression and Mel-18 could negatively regulate Bmi-1." (PMID 23874550, 2013). "The function of CBX7 in the carcinogenesis and progression of gastric cancer needs to be studied." (PMID 20723236, 2010). "Firstly, we analyzed the expression of CBX7 in several gastric cancer cell lines by western blot." (PMID 20723236, 2010). "As the expression of CBX7 in gastric cancer tissue samples correlated with lymph node metastasis, we hypothesized that CBX7 might also regulate cancer metastasis." (PMID 20723236, 2010). "One newly published paper revealed that CBX7 might be negatively regulated by miRNA421 in gastric cancer cell line, though the expression and function of CBX7 in gastric cancer are still unclear." (PMID 20723236, 2010). "The purpose of this study is to investigate the role of CBX7 in gastric cancer." (PMID 20723236, 2010). "CBX7 plays a role in the carcinogenesis and progression of gastric cancer and acts as an oncogene, and it may regulate tumorigenesis, cell migration and cancer metastasis partially via p16(INK4a) regulatory pathway." (PMID 20723236, 2010). "All these results suggest that CBX7 not only play important roles in tumorigenesis, but may also be involved in the progression and metastasis of gastric cancer." (PMID 20723236, 2010). "CBX7 was found to be overexpressed in gastric cancer cell lines and gastric tumors." (PMID 20723236, 2010). "In the present study, we first observed, to our knowledge, that the possible H3K9me3 binding protein CBX7 itself could initiate the specific formation of H3K9me3 via HMTase SUV39H2-dependent pathways in the p16 locus within gastric cancer cell lines." (PMID 21060834, 2010). "So the mechanisms of CBX7 in gastric cancer still need to be further studied." (PMID 20723236, 2010).
gastric cancer (continued). "CBX7 acts as an oncogene in the carcinogenesis and progression of gastric cancer, and it may regulate tumorigenesis, cell migration and cancer metastasis partially via p16(INK4a) regulatory pathway." (PMID 20723236, 2010). "Moreover, we found that expression of CBX7 in gastric carcinoma tissues with p16 methylation was significantly lower than that in their corresponding normal tissues, which showed a negative correlation with transcription of p16 in gastric mucosa." (PMID 21060834, 2010). "Besides, accumulated evidence shows that CBX7 has a similar function to BMI-1 in gastric cancer, suggesting that CBX7 may participate and function in a way related to BMI-1 regulation." (PMID 34659360, 2021). "Hence, we speculated that CBX7 might regulate stem cell-like properties of gastric cancer cells via miR-21." (PMID 29422082, 2018). "Therefore, we speculated that CBX7 might also be involved in the regulation of stem cell properties of gastric cancer cells." (PMID 29422082, 2018). "A prognostic gene model based on five CBX genes (CBX1, CBX2, CBX3, CBX7, and CBX8) predicted the overall survival of gastric cancer patients." (PMID 35969177, 2022). "CBX7 overexpression led to the upregulation of miR-21 in gastric cancer cells, while incubation with PI3K-specific inhibitor INK1197 abrogated CBX7-mediated expression of miR-21." (PMID 29422082, 2018). "We found that CBX7, a constituent of the polycomb repressive complex 1 (PRC1), plays an important role in maintaining stem cell-like characteristics of gastric cancer cells via the activation of AKT pathway and the downregulation of p16." (PMID 29422082, 2018). "Spearman rank correlation analysis showed positive correlations among the expression of CBX7 and phospho-AKT (pAKT), stem cell markers OCT-4, and CD133 in gastric cancer tissues." (PMID 29422082, 2018). "We overexpressed CBX7 in p16-expressing SGC-7901 and AGS gastric cancer cell lines and analyzed the expression of p16." (PMID 29422082, 2018). "Our results indicated that CBX7 overexpression facilitated the activation of AKT and ERK, while depletion of CBX7 downregulated the levels of p-AKT and p-ERK in gastric cancer cells." (PMID 29422082, 2018). "In the present study we found that knockdown of CBX7 resulted in increased p16(INK4a) expression and was accompanied by decreased transformed phenotype and migration ability, which suggested regulation of p16(INK4a) might be one of the important mechanisms of CBX7 in gastric cancer." (PMID 20723236, 2010). "However, in gastric cancer, CBX7 has been found to suppress p16 and activate the AKT-NF-kB signaling pathway to promote the stemness phenotype of gastric cancer cells." (PMID 39988672, 2025). "Moreover, we found a prognostic CBXs model comprising five genes (CBX1, CBX2, CBX3, CBX7, and CBX8) for gastric cancer patients." (PMID 35969177, 2022). "Although multivariate Cox proportional risk model analysis shows that CBX7 is not an independent prognostic factor for gastric cancer deterioration, the carcinogenesis role of CBX7 should not be underestimated." (PMID 34659360, 2021). "For example, Cbx7 has been identified to act as tumor suppressor in lung carcinoma by suppressing CCNE1 expression; conversely, it has been shown to act as an oncogene in gastric cancer by repressing p16 (INK4a)." (PMID 30357595, 2019). "To determine whether CBX7 may regulate GCSC phenotype via p16-independent mechanisms, we analyzed the effect of CBX7 overexpression in MKN28, a p16-negative gastric cancer cell line." (PMID 29422082, 2018). "Similarly, CBX7 downregulation increased chemosensitivity to epirubicin (EPI), whereas p16 shRNA restored chemoresistance in gastric cancer cells." (PMID 29422082, 2018). "In summary, we propose that CBX7-AKT-NF-κB-miR-21 pathway is an important determinant of GCSC phenotype and that targeting this pathway may provide new therapeutic opportunities for gastric cancer treatment." (PMID 29422082, 2018).
gastric cancer (continued). "Moreover, there was a positive correlation between the expression of CBX7 and stem cell markers OCT4 and CD133 in gastric carcinoma tissues." (PMID 29422082, 2018). "However, CBX7 does not appear to directly bind to PTEN promoter in gastric cancer cells (data not shown)." (PMID 29422082, 2018). "However, we found the correlation between the expression of CBX7 and p16(INK4a) in gastric cancer tissue samples by IHC analyses was not significant." (PMID 20723236, 2010). "Furthermore, expression of CBX7 positively correlates with the expression of pAKT in gastric carcinoma but not with the expression of pERK, suggesting that AKT may be an important downstream effector of CBX7 similar to BMI1." (PMID 29422082, 2018).
lung carcinoma (23 papers, 2014 to 2025). "One study has demonstrated that restoration of CBX7 expression increases the susceptibility to irinotecan treatment in human lung carcinoma cells." (PMID 31709304, 2019). "A similar mechanism is likely involved in human lung carcinogenesis since Cyclin E up-regulation, associated with the loss of CBX7 expression, has been observed in most of the human lung carcinomas analyzed." (PMID 24865347, 2014). "In addition, a study on human lung carcinomas showed that CBX7 restoration increases the susceptibility of irinotecan treatment for tumor cells." (PMID 35646140, 2022). "Also, Cacciola and colleagues revealed that restoration of CBX7 expression increased the susceptibility of human lung carcinoma cells to irinotecan treatment." (PMID 29190923, 2017). "Finally, CBX7 is proposed to play an anti-oncogenic role as measured by proliferation, and invasion, and CBX7 loss results in highly malignant phenotypes and poor prognoses in other entities (colon, bladder, pancreas, breast, liver and lung cancer)." (PMID 27449098, 2016). "In fact, the loss of CBX7 expression has been recently shown to be associated with increasing malignancy grade in colon, bladder, pancreatic, breast, gastric and lung carcinoma, whereas the retention of CBX7 expression correlates with a longer survival of the colon and pancreatic cancer patients." (PMID 24865347, 2014). "miR-19 plays the role of a tumor accelerator, as it promotes lung cancer cell proliferation by inhibiting the expression of CBX7." (PMID 40332376, 2025). "CBX7 expression is lost in a variety of cancers, such as urothelial carcinoma 16, colorectal cancer 17, breast cancer 18, pancreatic cancer 19 and lung cancer." (PMID 35342353, 2022). "For example, luciferase reporter assay has shown that miR-19 promotes the proliferation, migration of lung cancer cells by binding to the 3′-UTR of CBX7 mRNA and inhibits CBX7 expression at the translation level." (PMID 34659360, 2021). "Strikingly, miR-19 enhances cell proliferation via inhibition of CBX7 expression in nonsmall cell lung cancer cells." (PMID 31709304, 2019). "Very recently, we have also reported that reestablishment of CBX7 expression in two cell lines of human lung carcinoma, in which it was undetectable, yields a diminished proliferation and an improved apoptosis after drug exposure." (PMID 28259135, 2017). "Additionally, CBX7 was found to be downregulated in most cancers, including BC, cervical cancer, lung cancer and sarcoma." (PMID 36140750, 2022). "CBX7 was significantly down‐regulated in human lung carcinomas." (PMID 32894652, 2020). "Moreover, CBX7 was found to be significantly downregulated in human lung carcinoma tissues, which suggests that CBX7 functions as a tumor suppressor in these types of tissue by repressing cyclin E and CCNE1." (PMID 31211140, 2019). "The same result was achieved when CBX7 expression was restored in lung carcinoma cells." (PMID 28259135, 2017). "In lung cancer, CBX7 restoration resulted in decreased proliferation and increased apoptosis." (PMID 27449098, 2016). "Finally, we evaluated the expression of CBX7 and regulated genes in a panel of thyroid and lung carcinomas." (PMID 24865347, 2014). "Therefore, we analyzed CBX7 and the selected CBX7-regulated genes in human thyroid and lung carcinomas by qRT-PCR." (PMID 24865347, 2014). "Finally, quantitative RT-PCR analyses showed an inverse correlation between CBX7 and its down-regulated genes and a positive correlation with its up-regulated ones in human thyroid and lung carcinoma samples at different degree of malignancy." (PMID 24865347, 2014). "However, CBX7 is remarkably decreased in human lung cancer cells." (PMID 32894652, 2020). "In lung cancer, the expression of CBX1, CBX2, CBX3, and CBX5 was up-regulated, while CBX7 was down-regulated." (PMID 34966411, 2021). "Emerging reports showed that MMD, CBX7, FAP played an important role in the proliferation of lung cancer." (PMID 26870998, 2016).
lung carcinoma (continued). "used a weighted gene co-expression network analysis screening method to identify four key genes that are shared with OSA and lung cancer, namely modulator of apoptosis 1 (MOAP1), chromobox 7 (CBX7), platelet-derived growth factor subunit B (PDGFB), and mitogen-activated protein kinase 3 (MAP2K3)." (PMID 38605948, 2024). "According to the results obtained on cbx7 null MEFs, the levels of KRAS protein were found downregulated in A549 cells (human lung carcinoma line), overexpressing the CBX7 protein, in which we found higher miR-155 levels with respect to the same cells transfected with the control vector." (PMID 28259135, 2017). "Quantitative RT-PCR analyses in human thyroid and lung carcinoma tissues revealed a negative correlation between CBX7 and its down-regulated genes, while a positive correlation was observed with up-regulated genes." (PMID 24865347, 2014). "The function of CBX7 may occur at a transcriptional level since quantitative RT-PCR analysis showed a reduced CBX7-specific mRNA levels in colorectal cancer samples versus normal counterpart tissue (up to more than 50-fold) and cyclin E was upregulated in CBX7-KO mice in the lung cancer recearch." (PMID 28388562, 2017).